TWIST2 (twist family bHLH transcription factor 2)
Diseases named in the same sentence as TWIST2 in open-access papers (continued):
Sharing a sentence is not in itself a finding about the gene and the disease.
cancer (continued). "Given that M2 macrophages are known to induce epithelial‐mesenchymal transformation (EMT) in cancer cells, we explored the correlation between VSIG4 and several biomarkers associated with EMT processes (MMP9, SNAI1, SNAI2, VIM, TWIST1, TWIST2, CDH1, CDH2) in CRC through the TIMER2.0 website." (PMID 40405491, 2025). "Moreover, this transcriptome reprogramming was accompanied by significant increase in ZEB1, ZEB2 and TWIST2 EMT-TFs in cancer cells." (PMID 36936987, 2023). "The proteoglycans in cancer pathway (ecb05205) regulates proteoglycans in the extracellular matrix, which influences the behavior of cancer cells and their microenvironment by interacting with various cytokines (e.g., TWIST2), growth factors (e.g., HGF) and cell surface receptors (e.g., EGFR)." (PMID 36553455, 2022). "Finally, we examined the expression of genes that are known to be associated with migration and metastasis of cancer cells, and we observed a significant reduction in E-cadherin (CDH1), an inhibitor of differentiation 1 (ID1) and TWIST2." (PMID 34440702, 2021). "Furthermore, increased expression of Twist2 has been shown to confer an EMT phenotype in a small number of cancers, primarily breast and ovarian." (PMID 33139779, 2020). "The ability of TWIST2 to mediate the EMT in several types of cancer suggests that it may also be active in VM, but a definite role for TWIST2 in the VM process has not been reported." (PMID 25895023, 2015). "TWIST2 was reported to be a potential oncogene in human cancers." (PMID 24171926, 2013). "In addition, ectopically stable-expressed Twist2 was found to localize in the cytoplasm of cancer cells." (PMID 23133563, 2012). "Both Twist1 and Twist2 are known to mediate EMT in human cancers." (PMID 23133563, 2012). "Twist2 may also play a role in this process as has been shown in other cancer types." (PMID 33139779, 2020). "Cytoplasm Twist2 of cancer cells both in primary TC and the LM expressed E-cadherin and maintain their epithelial morphology, suggesting that the cancer cells in LM may have reacquired this morphology by a reversion of EMT (i.e. performing a mesenchymal to epithelial transition)." (PMID 23133563, 2012). "Understanding the discrete functions of TWIST2 and TWIST1 is imperative in the advancement of therapies to eradicate drug resistance and to improve the outcomes in cancer." (PMID 39941895, 2025). "TWIST2 governs the mesenchymal cell fate and epithelial–mesenchymal transition (EMT) critical for normal embryonic morphogenesis and cancer progression." (PMID 40869924, 2025). "Meanwhile, the critical transcription factors, including TWIST1, TWIST2, ZEB1, ZEB2, SNAI1 and SNAI2, participate in the EMT process, leading to cancer cell migration and invasion." (PMID 37794509, 2023). "The genes Twist1 and Twist2 have both been shown to play a role in the promotion of EMT and invasion in cancer." (PMID 35804837, 2022). "There exists a paucity of research on Twist2 in any cancer type; as such, these findings are important in ESCC as well as in other cancer types." (PMID 33139779, 2020). "Transcription factors of the Twist family (Twist1, Twist2), snail family (SNAI1/snail, SNAI2/slug), as well as ZEB family (ZEB1, ZEB2), control the EMT process in cancer." (PMID 24244294, 2013). "Several transcription factors (TFs) mediate the development of EMT, including SNAIL1/SNAIL2, TWIST1/TWIST2 and ZEB1/ZEB2, which are overexpressed in various carcinomas along with the under expression of the metastasis suppressor Raf Kinase Inhibitor Protein (RKIP)." (PMID 39335152, 2024). "As a transcription factor, TWIST2 has been found to promote and indicate EMT in various cancers." (PMID 33206629, 2020). "To further define cancer progression markers, we detected the expression of the CSCs surface marker EpCAM (also known as ESA), the self-renewal marker Nanog, the mesenchymal cell marker Twist2 and the epithelial cell marker E-cadherin by western blot analysis." (PMID 27253410, 2016).
cancer (continued). "Our results suggest that Twist2 is continuously localized in the cytoplasm of carcinoma cells that were stably selected, which may help carcinoma cells maintain the similar histological behavior in a noninvasive state." (PMID 23133563, 2012). "High mRNA levels of RKIP correlated negatively with those of SNAIL1, SNAIL2, TWIST1, TWIST2, ZEB1, and ZEB2 in several but not all carcinomas." (PMID 39335152, 2024).
head and neck tumors (1 paper, 2024). "In the field of head and neck tumors, the effect of heat therapy on the migration ability of human tongue squamous carcinoma may be related to TWIST2 protein, an important transcription factor for epithelial-mesenchymal transition, which has an important role in the malignant progression of tumors." (PMID 39027362, 2024).
TWIST2 also shares sentences with these, for which no sentence is quoted: Barber-Say syndrome (3 papers); ectodermal dysplasias (3); hematological malignancies (3); oculocutaneous albinism type 1 (2); thyroid cancer (2); acute kidney injury (1); Arthritis (1); behavioral disorders (1); benign breast diseases (1); brachydactyly (1); carotid atherosclerosis (1); cervical squamous cell carcinoma (1); cholangiocarcinoma (1); chondrodysplasia (1); chondroma (1); Coffin-Siris syndrome (1); colitis (1); congenital malformations (1); cyst (1); endometrial cancer (1); escherichia coli infection (1); eyelid (1); Failure to thrive (1); Fibroadenoma (1); fibrosis (1); focal facial dermal dysplasia type III (1); gallbladder carcinoma (1); genetic disorders (1); germinoma (1); glioblastoma (1).
A further 20 diseases each share a sentence with TWIST2 in 1 paper.